TWIST1 (twist family bHLH transcription factor 1)
Diseases named in the same sentence as TWIST1 in open-access papers (continued):
Sharing a sentence is not in itself a finding about the gene and the disease.
mesenchymal tumor (2 papers, 2017 to 2021). "As a mesenchymal tumor, it is not clear whether EMT plays a role in ES metastasis at all, but many genes implicated in EMT, including TWIST1, ZEB2, and SNAIL1, have also been implicated in ES metastasis." (PMID 29108227, 2017).
mesothelioma (2 papers, 2016 to 2022). A usually malignant and aggressive neoplasm of the mesothelium which is often associated with exposure to asbestos. "Further, vaccines against TWIST1 were recently shown to enhance CTLA-4 blockade in experimental mesothelioma immunotherapy approaches." (PMID 36176750, 2022). "However, we found a trend, for biphasic mesotheliomas (n = 21) toward exhibiting lower miR-186-5p (0.05 < P < 0.10) and higher TWIST1 expression, as compared to epithelioid mesotheliomas (n = 58)." (PMID 36176750, 2022).
metastatic melanoma (2 papers, 2016 to 2019). A melanoma that has spread from its primary site to another anatomic site. "For example, NC-related gene TWIST1 is highly expressed in metastatic melanoma and expression of MSX1 in melanocytes induced a dedifferentiated phenotype." (PMID 30641895, 2019). "Immunohistochemical analyses of a metastatic melanoma sample from the patient, from whom the ESP cells were established, revealed low ZEB1 and TWIST1 protein levels before treatment (Fig EV1C), confirming the increase in ZEB1 expression upon acquisition of resistance to vemurafenib." (PMID 27596438, 2016).
mycosis fungoides (2 papers, 2023 to 2025). Classical mycosis fungoides is the most common type of mycosis fungoides (MF), a form of cutaneous T-cell lymphoma, and is characterized by slow progression from patches to more infiltrated plaques and eventually to tumors. "The purpose of this RNA sequencing study was to investigate the biological mechanism underlying how the transcription factors (TFs) Twist1 and Zeb1 influence the prognosis of mycosis fungoides (MF)." (PMID 36900319, 2023).
myeloid leukemia (2 papers, 2015 to 2017). A clonal proliferation of myeloid cells and their precursors in the bone marrow, peripheral blood, and spleen. "In conclusion, our data substantiate the important pathogenic roles for TWIST-1 in myeloid leukemia and provide a new molecular marker for refining the risk classification of AML." (PMID 26023795, 2015). "We also determined whether the downstream signaling pathways of c-MPL underlie the TWIST-1-mediated effects in myeloid leukemia." (PMID 26023795, 2015). "In order to further substantiate our findings that TWIST-1 was overexpressed in myeloid leukemia, we analyzed TWIST-1 expression using several published datasets from the Oncomine databases." (PMID 26023795, 2015). "We were, therefore interested in determining the expression of TWIST-1 in immature myeloid leukemia cells." (PMID 26023795, 2015). "TWIST-1 knockdown impaired stem/progenitor cell colony-forming capacity of primary myeloid leukemia CD34+ cells." (PMID 26023795, 2015). "Mechanistically, c-MPL, which is highly expressed in myeloid leukemia cells and associated with poor prognosis, is identified as a TWIST-1 coexpressed gene in myeloid leukemia patients and partially contributes to TWIST-1-mediated leukemogenic effects." (PMID 26023795, 2015). "We performed transcriptome analysis to obtain clues of how TWIST-1 affected myeloid leukemia." (PMID 26023795, 2015). "Importantly, TWIST-1 expression in CD34+CD38− immature cells from myeloid leukemia patients (n = 6) was significantly higher compared with cord blood (CB) (n = 5)." (PMID 26023795, 2015). "Therefore, we next investigated the effects of down-modulation of TWIST-1 on the colony forming ability in myeloid leukemia stem/progenitor cells." (PMID 26023795, 2015). "Down-modulation of TWIST-1 in myeloid leukemia CD34+ cells impairs their colony-forming capacity." (PMID 26023795, 2015). "Next, we analyzed whether TWIST-1 expression level correlates with clinical outcome in myeloid leukemia." (PMID 26023795, 2015). "Therefore, although myeloid leukemias are heterogeneous in terms of phenotype, disease progression, prognosis, and response to therapy, TWIST-1 appears to be a common pathogenic factor for both AML and CML, suggesting its importance in the development of myeloid leukemias." (PMID 26023795, 2015). "To determine the functional interaction of TWIST-1 and c-MPL in regulating myeloid leukemia, we first examined the effect of c-MPL overexpression in U937 and K562 cells." (PMID 26023795, 2015). "Strikingly, the expression of TWIST-1 and c-MPL showed a significant trend toward positive correlation in myeloid leukemia samples." (PMID 26023795, 2015).
myeloid malignancies (2 papers, 2015 to 2018). "There have been some reports on the Twist1/Bmi1-associated aggressiveness in myeloid neoplasms." (PMID 26832848, 2015). "Although the link between Twist1 and Bcr-Abl translocation is unclear, Twist1 may still serve as an important predictive marker for treatment and prognosis in myeloid malignancies." (PMID 29685144, 2018).
osteomyelitis (2 papers, 2020 to 2023). An acute or chronic inflammation of the bone and its structures due to infection with pyogenic bacteria. "We found dramatically up-regulated expression of TWIST1 and macrophage recruitment at the infection site of implant-related osteomyelitis mice model." (PMID 32595631, 2020). "In chronic osteomyelitis, macrophage migration is regulated by the NF-κB/TWIST1 signaling pathway." (PMID 37744377, 2023). "It is somewhat unexpected that the up-regulated expression of TWIST1 and NANOG was only found in the cells from bone marrow but not in those from blood and the expression of ERBB2 was only down-regulated in the cells from blood in implant-associated osteomyelitis mice models." (PMID 32595631, 2020). "ERBB2, TWIST1, and NANOG were screened out as the most valuable osteomyelitis-related genes (OMRGs)." (PMID 32595631, 2020). "Therefore, up-regulation of TWIST1 and NANOG and down-regulation of ERBB2 might indicate activation of immune cells in response to S. aureus osteomyelitis." (PMID 32595631, 2020). "Results showed that TWIST1 and NANOG were significantly up-regulated in bone marrow cells, but not in peripheral blood cells, of S. aureus osteomyelitis mice." (PMID 32595631, 2020).
ovarian tumor (2 papers, 2016 to 2024). "Given the role of TWIST1 in regulating epithelial–mesenchymal transition, we further assessed whether there is a relationship between miR-192 level and epithelial morphology of ovarian tumours." (PMID 27041221, 2016).
sarcoidosis (2 papers, 2013 to 2014). Sarcoidosis is a multisystemic disorder of unknown cause characterized by the formation of immune granulomas in involved organs. "Using gene array data, we initially observed that bronchoalveolar lavage (BAL) cells from sarcoidosis patients displayed elevated mRNA of the transcription factor, Twist1, among many M1-associated genes compared to healthy controls." (PMID 24322444, 2013). "Results were similar to findings in sarcoidosis: Twist1 protein was elevated in both wild-type and PPARγ KO alveolar macrophages after MWCNT instillation." (PMID 25525507, 2014). "Findings showed a predominantly M1 phenotype in sarcoidosis alveolar macrophages together with a significant increase in Twist1 gene expression." (PMID 25525507, 2014). "We initially noted elevated Twist1 expression in sarcoidosis after analyzing gene array data from sarcoidosis and healthy control bronchoalveolar lavage (BAL) cells." (PMID 24322444, 2013). "Concurrently, BAL cells obtained from sarcoidosis patients and healthy controls validated gene array data: qPCR and protein analysis showed significantly elevated Twist1 in sarcoidosis compared to healthy controls." (PMID 24322444, 2013). "Findings suggest that Twist1 represents a PPARγ-sensitive alveolar macrophage M1 biomarker which is induced by inflammatory granulomatous disease in the MWCNT model and in human sarcoidosis." (PMID 24322444, 2013).
schizophrenia (2 papers, 2023 to 2024). A major psychotic disorder characterized by abnormalities in the perception or expression of reality. "In conclusion, this study suggests that altered SIK1/CRTC2/CREB1 and TWIST1/PI3K/Akt/GSK3β signaling pathways mediated by miR-25-3p is very likely to be associated with schizophrenia, revealing potential targets for the treatment and clinical diagnosis of schizophrenia." (PMID 36744005, 2023). "Furthermore, altered Akt/GSK3β signaling was widely reported to be associated with schizophrenia; and, it was pointed out that GSK3β can be phosphorylated at Ser9 by TWIST1 through the activation of the PI3K/Akt (Ser473) signaling." (PMID 36744005, 2023). "In the present study, we found that the TWIST1 protein levels were up-regulated by the repeated MK-801 administration, suggesting a possible connection with schizophrenia." (PMID 36744005, 2023). "Due to the close relationship between TWIST1 and neurodevelopment, it is worth investigating whether TWIST1 is involved in the pathogenesis of schizophrenia which is a neurodevelopmental mental disorder." (PMID 36744005, 2023). "This study investigated whether miR-25-3p-mediated SIK1/CRTC2/CREB1 and TWIST1/PI3K/Akt/GSK3β signaling pathways are present in an animal model relevant to schizophrenia." (PMID 36744005, 2023). "In addition, two possible downstream pathways of miR-25-3p, including the SIK1/CRTC2/CREB1 and TWIST1/PI3K/Akt/GSK3β signaling pathways, were examined with the schizophrenic rat model to explore their potential associations with schizophrenia." (PMID 36744005, 2023). "Therefore, the present study further explored whether the TWIST1/Akt/PI3K/GSK3β signaling pathway is abnormally modulated in schizophrenia." (PMID 36744005, 2023). "In conclusion, the present study suggests that miR-25-3p-mediated SIK1/CRTC2/CREB1 and TWIST1/PI3K/Akt/GSK3β signaling pathways could be potential therapeutic targets for future antipsychotic drugs and candidate diagnosis biomarkers of schizophrenia." (PMID 36744005, 2023).
small cell lung carcinoma (2 papers, 2019 to 2021). Small cell lung cancer (SCLC) is a highly aggressive malignant neoplasm, accounting for 10-15% of lung cancer cases, characterized byrapid growth, and early metastasis. "A study has reported that up-regulated lncRNA-LUADT1 is seen in small cell lung cancer that up-regulates Twist1 expression by sponging miR-15a-3p, thus encouraging cancer cell invasion and migration." (PMID 34738862, 2021).
Strabismus (2 papers, 2022 to 2023). A misalignment of the eyes so that the visual axes deviate from bifoveal fixation. "Using mouse models, they demonstrated that TWIST-1 deficiency led to disrupted organization of these muscles, resulting in strabismus." (PMID 37834867, 2023).
testicular cancer (2 papers, 2017 to 2022). A primary or metastatic malignant neoplasm that affects the testis. "Furthermore, a new connection between TWIST1 and the testicular cancer antigen MAGEA4 was recently reported for KYSE30 cells." (PMID 29299035, 2017).
uterine carcinosarcoma (2 papers, 2020 to 2022). A usually aggressive malignant neoplasm arising from the uterine corpus and less often the cervix. "A previous study suggested that in uterine carcinosarcomas, the ALK-mediated Akt/NF-κB/Twist1 pathway participates during the initial stage and regulates morphological alterations towards the sarcomatous phenotype." (PMID 36425467, 2022).
valvular heart disease (2 papers, 2012 to 2022). "In a rodent model of proliferative valvular heart disease, that over-expresses Twist1, several fibrillar collagens were dysregulated and collagen 2a1 was identified as a direct transcriptional target of Twist1." (PMID 22969750, 2012). "METTL3 can promotes osteogenic differentiation of human aortic valve interstitial cells by inhibiting twist-related protein 1 (TWIST1) expression through an m6A-dependent pathway, aggravating valve calcification and leading to the development of valvular heart disease." (PMID 35836571, 2022).
adrenocortical tumor (1 paper, 2022). "Assessment of the association among Twist1, fibronectin, vimentin and E-cadherin gene expression in adrenocortical tumor samples." (PMID 34669649, 2022).
allergic asthma (1 paper, 2025). A asthma with a basis in a pathological type I hypersensitivity reaction. "For instance, GATA2, TET2, and TWIST1 are enriched for more than one gene co-occurrence pair and are known to influence allergic asthma (63, –65)." (PMID 40504147, 2025).
arterial disorder (1 paper, 2021). An impairment of the structure or function of the blood vessels which carry blood away from the heart. "Intriguingly, recent evidence suggests TWIST1 acting as a crucial mediator of arterial disease development and vascular cell misbehavior." (PMID 33470057, 2021).
Arthritis (1 paper, 2025). Inflammation of a joint. "TWIST1 knockout leads to chronic joint inflammation in a murine arthritis model." (PMID 40761796, 2025).
astrocytoma (1 paper, 2017). "Immunohistochemistry analysis of TWIST1 in 269 infiltrating astrocytoma samples showed a stronger expression of TWIST1 associated with a higher malignancy grade." (PMID 29165393, 2017).
autoimmune disease (1 paper, 2015). A disorder resulting from loss of function or tissue destruction of an organ or multiple organs, arising from humoral or cellular immune responses of the individual to their own tissue constituents. "Being induced by proinflammatory cytokines, Twist1 may be increased in the periphery and / or in the brain in states of immune activation in infectious–and autoimmune diseases." (PMID 26361389, 2015).
B-cell non-Hodgkin lymphoma (1 paper, 2014). The most common type of non-Hodgkin lymphoma. "The aim of the present study was to investigate the expression level of TWIST1 in B-cell non-Hodgkin lymphoma (BNHL) and its association with the clinicopathological characteristics of BNHL." (PMID 25289047, 2014).
Barrett’s oesophagus (1 paper, 2018). "TFPI2, TWIST1, ZNF345 and ZNF569 methylation have promise as diagnostic biomarkers for Barrett’s oesophagus when used in combination with a simple and cost effective non-endoscopic cell collection device." (PMID 29084829, 2018).
benign prostatic hypertrophy (1 paper, 2019). "Fifty-five PCa and 48 benign prostatic hypertrophy tissue samples were tested for the presence of PLCε and Twist1 immunohistochemically." (PMID 31383001, 2019).
biliary tract cancer (1 paper, 2023). "Similarly, knockdown of ELF3 in biliary tract cancer cells resulted in upregulation of mesenchymal markers such as ZEB1/2, VIM and TWIST1 accompanied by the downregulation of KRT19." (PMID 36864480, 2023).
bladder tumors (1 paper, 2020). "Hence, a suitable impact was suggested, in particular for ECRG4, for discriminating BPH or urocystitis from bladder tumors, which is comparable with proposed biomarker candidates, like NID2 or TWIST1." (PMID 32046186, 2020).
calcific aortic valve disease (1 paper, 2024). "Recent research further highlights MEIS2’s role in calcific aortic valve disease (CAVD), where its inhibition promotes osteoblastic transdifferentiation and reduces Notch1 and Twist1 expression, making MEIS2 a potential target for CAVD prevention." (PMID 39758840, 2024).
carcinosarcoma (1 paper, 2025). A malignant tumor composed of a mixture of carcinomatous and sarcomatous elements. "EMT-associated transcription factors, including Snail1, SIP1, ZEB1, Twist1, and Slug, have been detected in carcinosarcomas, yet their expression patterns lack consistency, even among samples originating from the same organ." (PMID 41367455, 2025).
cardiac arrest (1 paper, 2025). Cessation of breathing and/or cardiac function. "Pro-EMT markers phospho-Smad1/5, Sox9, and Twist1 were downregulated in the AVC endocardium after cardiac arrest." (PMID 39932433, 2025).
Chronic colitis (1 paper, 2024). A chronic inflammatory disease of the large intestine (colon, cecum and rectum). "Genetic deletion or pharmacological inhibition of TWIST1 attenuates intestinal fibrosis induced by chronic colitis." (PMID 39042469, 2024). "Similar results were observed in a murine model of chemically induced chronic colitis, where TWIST1 deletion in fibroblasts (Twist1Δ/ΔCol1a2 mice) as well as treatment with harmine attenuated ECM deposition in the gut." (PMID 39042469, 2024).
chronic granulomatous disease (1 paper, 2013). Chronic granulomatous disease (CGD) is a rare primary immunodeficiency, mainly affecting phagocytes, which is characterized by an increased susceptibility to severe and recurrent bacterial and fungal infections, along with the development of granulomas. "Current findings suggest that alveolar macrophages exhibit Twist1 expression when an M1 stimulatory milieu, as found in chronic granulomatous disease, dysregulates pulmonary homeostasis." (PMID 24322444, 2013).
chronic kidney disease (1 paper, 2022). Impairment of the renal function secondary to chronic kidney damage persisting for three or more months. "Although the Twist1 has been well studied in kidney fibrosis by regulating renal tubular epithelial cell and migration of tumor cell, little is known about the Twist1 in regulation of renal monocyte/macrophage function in normal and chronic kidney disease." (PMID 35182235, 2022).
Cirrhosis (1 paper, 2018). A chronic disorder of the liver in which liver tissue becomes scarred and is partially replaced by regenerative nodules and fibrotic tissue resulting in loss of liver function. "Most importantly, Twist1 was high expression in patients with cirrhosis which was positively correlated with miR-214 level." (PMID 29915227, 2018). "Furthermore, we observed high expression of Twist1 in clinical cirrhosis samples, which was positively correlated with miR-214 expression." (PMID 29915227, 2018).
colitis (1 paper, 2024). Inflammation of the colon. "TWIST1 deletion in vivo was also associated with a reduction in FAP expression in fibroblasts isolated from the colon of Twist1Δ/ΔCol1a2 mice compared with their littermates after DSS-induced colitis." (PMID 39042469, 2024).
dysplasia (1 paper, 2025). A usually neoplastic transformation of the cell, associated with altered architectural tissue patterns. "TWIST1 up-regulation was observed in at-risk BE samples years before the emergence of any microscopic signs of malignancy (dysplasia/EAC)." (PMID 40620772, 2025).
endometrioid carcinoma (1 paper, 2025). "TWIST1 was highly expressed in high-grade serous tissues but not statistically significant in endometrioid carcinoma of OC patients compared with normal ovarian tissues." (PMID 40424038, 2025).
endometrioid endometrial carcinoma (1 paper, 2020). "When compared with the normal endometrium, SNAI1 was upregulated as early as in the noninvasive (stage 1A) and myoinvasive (stage 1B) tumors, followed by the expression of TWIST1, ZEB1, and SNAI2 in the myoinvasive (stage 1C) tumors of endometrioid endometrial carcinoma." (PMID 32370157, 2020).
ependymoma (1 paper, 2015). A WHO grade II, slow growing tumor of children and young adults, usually located intraventricularly. "However, our combined approach identified novel potential biomarker candidates in ependymoma with a known relationship to cancer: ERRB2, EGFR, TWIST1, CDK4, HDAC9, and ARHGEF5 genes." (PMID 26185765, 2015).
fatty liver (1 paper, 2021). "The level of TWIST1 protein in the severe fatty liver group was the same as that in the control group." (PMID 33879188, 2021). "TWIST1 serum protein levels varied greatly with the severity of disease, with significantly lower levels in the mild fatty liver group and significantly higher levels in the moderate fatty liver group." (PMID 33879188, 2021).
gastric tumors (1 paper, 2016). "Real-time PCR on samples from iLgr5;GLI2A gastric tumors revealed upregulation of mRNA encoding multiple EMT markers, including Snail1 (8.1-fold), Snail2/Slug (2.5-fold), FSP1 (3.6-fold), and Twist1 (3.9-fold)." (PMID 26859571, 2016).